DAPK1 (death associated protein kinase 1)
Diseases named in the same sentence as DAPK1 in open-access papers (continued):
Sharing a sentence is not in itself a finding about the gene and the disease.
epilepsy (12 papers, 2007 to 2024). A brain disorder characterized by episodes of abnormally increased neuronal discharge resulting in transient episodes of sensory or motor neurological dysfunction, or psychic dysfunction. "The excitotoxicity of GluN2B phosphorylation elicited by DAPK1 activation is also involved in neuronal loss caused by epilepsy, toxic Aβ treatment, stress-related depression and TBI insult." (PMID 38195518, 2024). "We also found that Kcna1, which has been implicated to be involved in epilepsy, was highly upregulated in DAPK1-KO mice." (PMID 37047515, 2023). "Collectively, these results indicate that pretreatment with the ERK inhibitor U0126 reduces mouse susceptibility to epilepsy and protects against the neuronal damage induced by KA by inhibiting DAPK1 activity." (PMID 35742817, 2022). "The application of a specific ERK inhibitor or synthetic blocking peptide to bind ERK and DAPK1 reduced susceptibility to epilepsy and protected neurons from apoptosis in both in vitro and in vivo models." (PMID 35742817, 2022). "Death-associated protein kinase 1 (DAPK1) expression has been shown to be upregulated in the brains of human epilepsy patients compared with those of normal subjects." (PMID 34239362, 2021). "Mechanistically, NR2B phosphorylation was attenuated in DAPK1 KO mice, suggesting that DAPK1 ablation decreased seizure susceptibility in vivo and has therapeutic potential for epilepsy." (PMID 34239362, 2021). "Death-associated protein kinase 1 (DAPK1, up 2-fold) is expressed in neurons and overexpressed and activated in seizure disorders." (PMID 18021406, 2007). "Because DAPK1 KO decreases susceptibility to epilepsy, we next aimed to examine whether DAPK1 KO protects against neuronal damage induced by KA." (PMID 35742817, 2022). "Death-associated protein kinase 1 (DAPK1) expression is highly increased in the brains of epilepsy patients; however, the underlying mechanisms by which DAPK1 influences neuronal injury and its therapeutic effect on glutamate excitotoxicity have not been determined." (PMID 35742817, 2022). "The results demonstrate that suppressing DAPK1 activity may have potential as a therapeutic option for reducing susceptibility to epilepsy." (PMID 34239362, 2021). "DAPK1 dysregulation has been detected in several neurological disorders, including Alzheimer's disease, cerebral ischaemia, epilepsy and depression 11-13." (PMID 39479447, 2024). "First, MA@RT-HMSN administration significantly inhibited DAPK1 expression, promoted autophosphorylation at Ser308 to negatively regulate DAPK1 activity and reduce Ca2+ levels in acute epilepsy." (PMID 39479447, 2024). "Further, our study showed that kainic acid (KA) promotes DAPK1 activity by upregulating the ERK-mediated Ser735 phosphorylation in a mouse epilepsy model." (PMID 38195518, 2024). "The present work provides not only a feasible platform for precise inhibition of DAPK1 in inflammatory lesions of the brain but also a promising targeted therapy for epilepsy." (PMID 39479447, 2024). "Activation of DAPK1 by extracellular signal-regulated kinase (ERK) increases neuronal apoptosis in an epilepsy mouse model, while DAPK1 gene depletion alleviates neuronal cell death." (PMID 37047515, 2023). "Levels of DAPK1 are significantly increased in brain samples from patients with epilepsy compared with those in control subject samples." (PMID 35742817, 2022). "Our findings thus provide novel insights into the key roles of the ERK and DAPK1 molecular pathways in modulating seizures and suggest new therapeutic approaches for human epilepsy." (PMID 35742817, 2022). "We further studied the effects of DAPK1 on seizure behavior and brain damage in KA-induced epilepsy mouse models on a DAPK1 KO background." (PMID 35742817, 2022). "Ablation of DAPK1 expression by gene KO or suppression of DAPK1 activity by a small molecule significantly reduces seizure phenotypes and epilepsy development." (PMID 34239362, 2021).
epilepsy (continued). "Future studies should include intensive cross-talk between DAPK1 and its interacting partners and/or downstream targets in the development of epilepsy." (PMID 34239362, 2021). "Combined together, these results suggest that DAPK1 regulation is a novel mechanism for the control of both acute and chronic epilepsy and provide new therapeutic strategies for the treatment of human epilepsy." (PMID 34239362, 2021). "Taken together, our study demonstrates a novel role of DAPK1 regulation and offers a novel therapeutic strategy for treating human epilepsy by targeting DAPK1." (PMID 34239362, 2021). "Because the expression of DAPK1 is increased in epilepsy patients, we first characterized the short-term changes in DAPK1 expression after acute PTZ treatment." (PMID 34239362, 2021). "Recently, overexpressed DAPK1 in endothelial and astrocytic cells from epilepsy patient brains was shown to regulate cell death by hypoxia in epileptic pathological conditions." (PMID 34239362, 2021). "Targeted inhibition of DAPK1 decreases neural activity, ameliorates inflammatory responses, prevents gliosis, reduces apoptosis, and promotes the recovery of cognition, thus exerting neuroprotective and therapeutic effects on epilepsy." (PMID 39479447, 2024). "It was shown that the activity of DAPK1 was increased and its expression was upregulated in the hippocampus of epilepsy patients, which may contribute to neuronal damage by mediating cell death signalling pathways." (PMID 39479447, 2024). "In this study, we focused on the modulation of DAPK1 in epilepsy." (PMID 39479447, 2024). "Our previous studies have validated that DAPK1 plays a critical role in the development of epilepsy and might be a potential target for neuronal protection in epilepsy." (PMID 37047515, 2023). "Our group and other groups have shown that DAPK1 may play a critical role in epilepsy pathophysiology." (PMID 35742817, 2022). "In the current study, an ERK inhibitor not only reduced susceptibility to epilepsy but also protected neurons from excitotoxicity by suppressing DAPK1 activity, indicating that DAPK1 may be a downstream effector of ERK in KA-induced epilepsy models." (PMID 35742817, 2022). "Since DAPK1 expression is upregulated in epilepsy patients, we aimed to examine whether DAPK1 expression and activity are increased by KA before GTCSs." (PMID 35742817, 2022). "DAPK1 KO displayed a potent protective effect on neuronal cell death after epilepsy." (PMID 35742817, 2022). "Since melatonin has been shown to suppress epilepsy-related seizures and DAPK1 has been targeted by E3 ubiquitin ligases 23, 60, melatonin may regulate DAPK1 levels in a posttranslational manner in the development of kindled seizures." (PMID 34239362, 2021). "Moreover, pharmacological inhibition of DAPK1 activity exerted rapid antiepileptic effects in both acute and chronic epilepsy mouse models." (PMID 34239362, 2021). "In this study, we aim to clarify whether and how DAPK1 is regulated in epilepsy and whether targeting DAPK1 expression or activity has a protective effect against epilepsy using seizure animal models." (PMID 34239362, 2021). "Interestingly, we discovered that the expression and activity of DAPK1 was upregulated in the epilepsy model induced by chronic PTZ administration." (PMID 34239362, 2021). "Although previous studies indicate that DAPK1 may be important for the development of epilepsy, the molecular mechanisms of DAPK1 and its therapeutic efficacy against epileptic seizures remain largely unresolved." (PMID 34239362, 2021). "The requirement of DAPK1 catalytic activity for its proposed cell functions and the elevation of catalytic activity of DAPK1 in injured neurons in models of neurological diseases, such as ischemia and epilepsy, validate that DAPK1 can be taken as a potential therapeutic target in these diseases." (PMID 27447806, 2017). "Thus, DAPK1 has potential as a novel therapeutic target for epilepsy." (PMID 39479447, 2024).
epilepsy (continued). "Moreover, our findings imply that the potassium voltage-gated channel subfamily A member 1 (Kcna1) may be involved in the modulation of DAPK1 in epilepsy." (PMID 37047515, 2023). "Furthermore, it should be warranted whether the combination treatment of melatonin and DAPK1 inhibitor has synergistic effects on epilepsy." (PMID 34239362, 2021). "During the progression of epilepsy in the PTZ-kindling model of chronic epilepsy, the seizure grade was increased, which was positively correlated with DAPK1 expression levels as evidenced by the Pearson correlation coefficient (R2 = 0.9525)." (PMID 34239362, 2021). "Our study has thus deciphered a key role of DAPK1 in modulating PTZ-induced seizures and could provide insights on the development of novel therapeutic approaches for human epilepsy." (PMID 34239362, 2021). "Based on the finding that pharmacological inhibition of DAPK1 activity produces rapid and potent antiseizure effects in both PTZ-induced acute and kindling animal models, DAPK1 inhibition might be a promising option for epilepsy interventions." (PMID 34239362, 2021). "Nevertheless, whether the expression or activity of DAPK1 is regulated in epilepsy remains incompletely understood and whether inhibition of the function of DAPK1 exerts antiepileptic effects in animal models has not been determined." (PMID 34239362, 2021). "To investigate the effect of DAPK1 inhibition on the development of kindled seizures, we first examined whether the suppression of DAPK1 expression plays a protective role in epilepsy by administrating repeated PTZ doses of 35 mg/kg in the WT and DAPK1 KO mice." (PMID 34239362, 2021). "Since we report here, for the first time to our knowledge, that ERK is an upstream regulator of DAPK1 activity in TLE, further studies are warranted to determine whether ERK is required for DAPK1 activation in other neurodegenerative diseases, including different subtypes of epilepsy." (PMID 35742817, 2022).
hepatocellular carcinoma (12 papers, 2011 to 2025). A malignant tumor that arises from hepatocytes. "Amcinonide as a corticosteroid has been reported to effectively reverse the expression of the oncogene DAPK1 (death-associated protein kinase 1) in liver carcinoma." (PMID 32724299, 2020). "The mechanism through which death-associated protein kinase 1 (DAPK1) causes hepatocellular carcinoma (HCC) progression remains unclear." (PMID 35935258, 2022).
head and neck cancer (11 papers, 2012 to 2025). A primary or metastatic malignant neoplasm affecting the head and neck. "Hypermethylation of DAPK1 has been found to be involved in head and neck cancers, papillary thyroid cancer, and even brain metastases of various solid tumors." (PMID 28934284, 2017). "Methylation of DAPK1 is an early event in the carcinogenesis of head and neck cancers." (PMID 22645613, 2012).
ischemia (11 papers, 2012 to 2025). A hypoperfusion of the BLOOD through an organ or tissue caused by a PATHOLOGIC CONSTRICTION or obstruction of its BLOOD VESSELS, or an absence of BLOOD CIRCULATION. "In skeletal and cardiac muscle, DAPK1 is implicated in muscle cell differentiation and survival, with its expression in these tissues being linked to stress responses, such as ischemia, where DAPK1 may facilitate cell death in response to oxidative stress." (PMID 40918124, 2025). "The activation of DAPK1 in ischemia is likely mediated by the N-methyl-D-aspartate receptor (NMDAR)-induced Ca2+ influx and the subsequent dephosphorylation at Ser308 of DAPK1 by the calcineurin phosphatase." (PMID 38195518, 2024). "In the brain, it has been recently reported that ischemia downregulates miR-98-5p, and that experimentally upregulated miR-98-5p in stroked mice inhibits ROS production, reduces infarction and suppresses DAPK1 signaling." (PMID 33265962, 2020). "In fact, several cross-IP assays (IP with antibodies against DAPK1 or LRRFIP1) revealed an association and coexistence of the 2 proteins after ischemia in adult rat brain or after OGD or NMDA treatment in primary culture neurons." (PMID 33265962, 2020). "In addition, DAPK1 modulates brain damage via the NMDA receptor or alpha-amino-3-hydroxy-5-methyl-4-isoxazole propionic acid (AMPA) receptor by ischemia and inhibition of DAPK1 activity, which contributes to neuroprotective effects in a mouse model of ischemia." (PMID 37047515, 2023). "We have identified for the first time LRRFIP1 as a DAPK1 partner, which we found up-regulated by OGD in the neuronal DAPK1 interactome, this being in line with the previously reported involvement of LRFFIP1 in ischemia." (PMID 33265962, 2020). "The requirement of DAPK catalytic activity for its proposed cell functions and the validation of protein kinases as therapeutic targets in human disease make the identification of substrates of DAPK1 in ischemia extremely important." (PMID 27447806, 2017).
leukemia (10 papers, 2009 to 2025). A malignant (clonal) hematologic disorder, involving hematopoietic stem cells and characterized by the presence of primitive or atypical myeloid or lymphoid cells in the bone marrow and the blood. "Our results showed that hypermethylation of DAPK1 gene was associated with the increased risk of leukemia (P<0.0001, OR = 28.85, 95% CI = 5.54–150.14)." (PMID 24810788, 2014). "Our study identified the aberrant DNA methylation at DAPK1 gene was a risk factor for leukemia." (PMID 24810788, 2014). "Given that the sensitivity of M-MSP of miR-34b/c and DAPK1 is 10-3, and that the leukemia infiltration ranged from 36% to 95% (median: 64%), our results are still valid even without CD19 cell sorting of primary samples." (PMID 24559316, 2014). "Meta-analysis of DAPK1 methylation with leukemia was carried out in 3 studies among 29 controls and 169 cases." (PMID 24810788, 2014). "In CLL, apoptosis in leukemia cells is inhibited by enhanced production of B-cell lymphoma 2 (BCL2) and methylation of the promoter region of death-associated protein kinase 1 (DAPK1)." (PMID 22735547, 2012). "Our previous investigation evaluated DAPK1 expression in several gynecological cancer cell lines (cervical, ovarian, and breast) and the cell lines of different origin (colon, lung, and leukemia), as well as primary normal cells (keratinocytes and fibroblasts)." (PMID 40563561, 2025). "The current study evaluated a small range of gynecological cancer cell types (cervical, ovarian, breast) and other cancer cell types (colon, lung, leukemia), as well as primary normal cells (keratinocytes, fibroblasts) for the expression of DAPK1 via western blotting." (PMID 35154442, 2022).
Parkinson disease (10 papers, 2014 to 2025). A progressive degenerative disorder of the central nervous system characterized by loss of dopamine producing neurons in the substantia nigra and the presence of Lewy bodies in the substantia nigra and locus coeruleus. "In Parkinson’s disease (PD), DAPK1 hyperactivation is linked to neuronal apoptosis and synaptic injury, exacerbating disease progression." (PMID 39926603, 2024). "Research on ROCO proteins significantly intensified since the identification of links between ROCO proteins and human disease, notably, leucine-rich repeat kinase 2 (LRRK2) with Parkinson’s disease (PD) and death-associated protein kinase 1 (DAPK1) with cancer (Marín, 2006; Terheyden, 2018)." (PMID 39246816, 2024). "DAPK1 was also a direct target of miR-26a, and miR-26a/DAPK1 signaling cascades were associated with cellular pathologies in neurodegenerative disorders such as Parkinson's disease." (PMID 31093272, 2019). "Research into the function of these domains exploded with their identification in a number of proteins linked to human disease, including leucine-rich repeat kinase 2 (LRRK2) and death-associated protein kinase 1 (DAPK1) in Parkinson’s disease and cancer, respectively." (PMID 24981771, 2014). "DAPK1 knockdown exerts rapid antidepressant-like effects, and DAPK1 ablation in dopaminergic neurons reverses abnormalities in mouse Parkinson’s disease (PD) models after long-term 1-methyl-4-phenyl-1,2,3,6-tetrahydropyridine (MPTP) exposure." (PMID 35742817, 2022). "This phenomenon has previously been observed for DAPK1 in both Alzheimer’s and Parkinson’s disease mouse models." (PMID 33250715, 2020).